TNF (tumor necrosis factor)
Diseases named in the same sentence as TNF in open-access papers (continued):
Sharing a sentence is not in itself a finding about the gene and the disease.
infection (continued). "Four weeks post infection with M.tb HN878, we observed a significant increase in circulating IFN-γ, TNF-α, IL-1β, IL-2, IL-6, IL-12p70, IL-17A/F, IL-15, and IL-33 levels in mice immunized with ID93+EmT4TM compared to saline controls." (PMID 40285479, 2025). "At 48 h post-infection, U937 macrophages infected with LRV-1+ isolates exhibited elevated concentrations of TNF-α and IL-1β and reduced IFN-γ, compared to those infected with LRV-1− isolates." (PMID 41471220, 2025). "Disseminated Mab infections have been reported in immunocompromised individuals, with innate, acquired, or medication-induced defects in the IL-12-IFN-γ and TNF-α pathways." (PMID 41294882, 2025). "Comparison of serum levels of TNF-α, IL-6, and IFN-γ among patients with different severities of infection." (PMID 40677522, 2025). "The qPCR experiment showed that the transcription levels of IL-1β, IL-6, and TNF-α in the circ-ZNF277 suppressed THP-1 cells were lower than those in the control THP-1 cells at 0, 12, and 24 h post-infection (p < 0.001)." (PMID 39996735, 2025). "However, in the later phase of infection, the virus may interfere with TNFα activity." (PMID 40103806, 2025). "The authors suggested that reactive inflammatory disease resulted from insufficient sterilization of infection by SKG mice, as there was decreased IFN-γ and IL-17 productions, but excessive TNF-α." (PMID 40366144, 2025). "Conversely, upon losing control of the infection, T cells would differentiate toward effector memory (TEM) cells with reduced IL-2 production and increased IFNγ and TNF secretion." (PMID 41159744, 2025). "Infections, such as SARS‐CoV‐1, can activate DCs to produce inflammatory cytokines (TNF‐α, IL‐6) and chemokines (MIP‐1α, RANTES, IP‐10, MCP‐1, CCL3, CXCL10)." (PMID 40405557, 2025). "The mRNA level of cytokines, including IL-1β, IL-10, IL-8, TNF-α, IFN-α, and IFN-γ, was detected in MARC-145si14-3-3γ and MARC-145siNC cells following infection with TA-12." (PMID 40704900, 2025). "In a study of host responses to high-dose H10N5 infection in mice, the levels of cytokines including PRR, IFN, TNF, IL, and chemokines increased in lung tissue significantly." (PMID 40626651, 2025). "The production of IFN-γ, TNF, and IL-10 was reduced in the draining lymph node, as well as the total number of CD3+CD4+IFN+ and CD3+CD4+TNF+ T cells in the infection site." (PMID 40982482, 2025). "Compared with those in the WT infection group, the expression levels of common proinflammatory factors in the ΔL-lectin group were significantly lower, including IFNγ, IL1β, IL6, IL8, and TNFα." (PMID 40076391, 2025). "Research has shown that inflammatory factors such as IL-1β, IL-6, IL-8, and TNF-α can induce and recruit various types of white blood cells to participate in immune responses, which may lead to tissue damage and affect the healing of infections if present long-term." (PMID 40529353, 2025). "We observed reduced TNF‐α expression in PRF‐ and PRP‐treated groups at day 16 after burn injury and infection compared to control group, while it was significantly increased in AG‐treated group." (PMID 39829200, 2025). "Immunofluorescence results demonstrated that β-acids accelerated wound healing by markedly reducing IL-6 and TNF-α, increasing VEGF levels, and suppressing infection." (PMID 41415825, 2025). "At 5 days post-infection (dpi), mice infected with the moderately virulent AQP-RE strain exhibited significantly higher expression of pro-inflammatory cytokines IFN-γ and TNF-α compared to those infected with the virulent CL Brener clone (p < 0.05)." (PMID 41394106, 2025). "An altered cytokine profile is normally observed during these infections, including reduced levels of IFN-γ and TNF-α in bovine monocyte and macrophage subsets." (PMID 40943382, 2025). "Classical monocytes are recruited to infection and inflammation sites via the CCL2/CCR2 pathway, releasing cytokines like TNF-α and iNOS to kill pathogens and enhance adaptive immunity." (PMID 40370772, 2025).
infection (continued). "TNF-α release was only detected in apical supernatants and was significantly elevated by LF82 infection." (PMID 41163391, 2025). "The expression of IL-1β, IFN-α2, IFN-γ, TNF-α, MCP-1 (CCL2), IL-6, IL-8 (CXCL8), IL-10, IL-12p70, IL-17A, IL-18, IL-23, and IL-33 was assessed in apical washes at different time points after infection using a 13-plex immunoassay." (PMID 40143308, 2025). "These functions act synergistically with the cytotoxic CD8+ TEM, which, upon viral reactivation, migrate to infection sites, secrete IFN-γ and TNF-α, and eliminate infected cells through granzyme B-mediated cytotoxicity." (PMID 41425559, 2025). "Levamisole significantly inhibited IL-1β, IL-6, IL-8, IL-18, TNF-α, and COX-2 mRNA expressions in the spleen compared to the infection group (p < 0.001)." (PMID 40427533, 2025). "The macrophages released high levels of TNF, up to 8 ng/mL, consistent with a previous study, but modest levels of NS1 after 2 days of infection (~500 ng/mL)." (PMID 41218088, 2025). "After infection by L. (L.)amazonensis, the IFN-γ and TNF-α secretion was also the highest in mice vaccinated with the chimeras." (PMID 40666521, 2025). "Following the infection of RAW264.7 cells with SFTSV at the MOI of 200 for 24 or 48 h, the levels of IL-1β, IL-6, IL-10, TNF-α, and MCP-1 were measured by using qPCR." (PMID 41472750, 2025). "Intriguingly, S25 phosphorylation is described as a pro-survival checkpoint in TNF signaling, as it has been shown to confer resistance to RIPK1-mediated cell death by preventing RIPK1 auto-activation in murine models of infection and inflammation." (PMID 41315176, 2025). "In conclusion, serum TNF-α, IL-6, and IFN-γ levels are significantly elevated in DFI patients, and all three cytokines serve as potential biomarkers for assessing infection severity and prognosis." (PMID 40677522, 2025). "Following VMV infection, BAL macrophage numbers are elevated and AlvMφ display an activated phenotype with secretion of IL-8, IL-6, IL-10, GM-CSF, TNF-α, IL-1β, and TGF-β." (PMID 39796262, 2025). "Multiple innate immune signaling pathways are activated after 6 h of infection of F81 cells with FPLV, such as NF-κB, NLR, RLR, TNF, IL-17, and JAK-STAT signaling pathways." (PMID 40872699, 2025). "In mycobacterium tuberculosis, T-cells such as Th1 and Th2 cells in conjunction with cytokines such as TNF-α and IFN-Υ play a role in controlling this infection." (PMID 41155579, 2025). "On day 3 post-infection, cytokine profiling revealed significantly higher levels of IFN-α, IFN-β, TNF-α, CXCL-1, and IL-6 in the lungs of mice infected with the G-extended virus compared to the Δ7AA virus." (PMID 40076707, 2025). "We previously found that EBV also upregulates IL-18, TNF-α, and IFN-γ mRNAs within the first week of infection." (PMID 40674368, 2025). "In the early stage of infection, ELISA results showed that exogenous PGD2 significantly promoted the secretion of TNF-α, IL-1β, and IL-6 in BMDMs and endometrial tissues, suggesting its role in enhancing the inflammatory response during early infection." (PMID 40874199, 2025). "GFP-tagged GSDMD was expressed in RIPK3 expressing HeLa (HeLa-RIPK3) cells, in which we previously reported that co-treatment of TNF and TAK1 inhibitor mimics pathogen infection and induces mitochondrial ROS." (PMID 40533460, 2025). "PD-1 can reduce levels of inflammatory cytokines, including TNFα, IL-1β, IL-6, and iNOS, suggesting that an increase in eosinophil numbers may act to reduce inflammation and tissue damage induced by catheterization and infection, consistent with our observations here of eotaxin effects during CAUTI." (PMID 40980878, 2025). "It has been shown that IL-6 and TNF-α are signaling components of ADE, and elevated levels of IL-6 in RSV patients indicate a severe infection." (PMID 40557164, 2025).
infection (continued). "To determine the influence of coexistent Ss infection on type 1, type 17, and proinflammatory cytokines in TBI, we measured the QFT supernatants levels of IFN-γ, TNF-α, IL-2, IL-17, IL-22, IL-1α and IL-1β in TBI+Hel+ and TBI+Hel- individuals." (PMID 41583474, 2025). "In this study, we observed significant upregulation of IL-6, IL-8, and TNF-α mRNA levels, confirming the successful establishment of a GPS infection model in 3D4/21 cells." (PMID 40636259, 2025). "The results of ELISA showed that PECP was able to significantly inhibit the elevation of cytokines TNF‐α, IFN‐γ, and IL‐6 and chemokines IP‐10, MCP‐1, and MIP‐1α after infection in mice." (PMID 40757669, 2025). "While the tested MAPK inhibitors had variable effects on COX-2 protein levels induced by F. nucleatum or TNF alone, only inhibition of p38 significantly suppressed the synergistic induction of COX-2 in GFs subjected to simultaneous stimulation and infection." (PMID 40178270, 2025). "The concentration of chemokines CxCL1/KC/GRO-α, CxCL2/MIP-2, CCL5/RANTES and cytokines TNF-α, IL-1β, IFN-γ, IL-5, IL-6, IL-9, IL-10, IL-13, IL-17, IL-23 circulating in blood were measured in experimental animals on day 15 post-infection." (PMID 40445994, 2025). "Infection of THP-1 cells with MAP upregulated MCT4 expression (2 folds) and resulted in a significant increase in lactate export (1.3 folds), TNFα (13.8 folds), and IL-6 (1.3) via TLR2 activation." (PMID 40297589, 2025). "In agreement, after infection, the F3 vaccine determined the maximal IFN-γ/IL10 ratios (five- to eight-fold higher than the chimeras) and the most potent TNF-α/IL-10 ratios (eight- to 11-fold higher than the chimeras)." (PMID 40666521, 2025). "Notably, the significant increase in TNFα expression observed in the brain on day 7 post-infection implies that the central nervous system may play a role in regulating inflammation and controlling the spread of infection." (PMID 40723580, 2025). "Functionally, these molecular alterations translated into a diminished secretion of key inflammation and infection mediators, such as interleukin-6 (IL-6) and C-C Motif chemokine ligand 5 (CCL5) upon TNF-a stimulation." (PMID 41050669, 2025). "By day 10 post-infection, infected mice exhibited significantly elevated levels of MCP-1, IFN-γ, IL-12 p70, TNF-α, IL-6, and IL-10 in the brain, indicating a strong inflammatory response." (PMID 40078875, 2025). "Despite partial IgG induction upon repeated dosing, PEGylated phages maintained superior PK and significantly suppressed infection-driven IL-6, IFN-γ, TNF-α, and IL-1β, normalizing cytokine profiles toward baseline." (PMID 41309396, 2025). "Several cytokines (TNF, IL-1β) and chemokines (CXCL10, CCL2, CCL5) were reduced in the brains of Rag1–/– animals at day 14 after infection, which were restored or exceeded WT levels mainly with Th1 adoptive transfer, whereas Th17 cells were less effective." (PMID 39989461, 2025). "During the early phase of infection (5 dpi), AQP-RE induced a rapid increase in IFN-γ and TNF-α expression, consistent with strong innate immune activation and limited capacity to suppress early inflammation." (PMID 41394106, 2025). "TNF and IL1B, two key genes identified in the study, were selected for validation of their differential expression levels between the infection and control groups using qRT-PCR." (PMID 40725488, 2025). "Infection with L. monocytogenes led to a significant increase in the mRNA levels of IL6, CXCL8, TNF, and IFNG (p < 0.01 for IL6, p < 0.001 for other cytokines), along with a significant decrease in transcription level of IL10 (p < 0.001)." (PMID 41376047, 2025). "Since hsa-miR-3925-5p has a high coding number and currently available research data on it are limited, we focused on analyzing the potential role of the miR-34a-3p/TNF and miR-190a-3p/IL1B axes in the immune response process following DCs infection with M.tb." (PMID 40725488, 2025).
infection (continued). "A Th1-mediated adaptive immune response plays a pivotal role in infection control by driving the production of cytokines such as IFN-γ, IL-2, and TNF-α." (PMID 41310729, 2025). "In the lymph nodes, we observed significant increases in the levels of IL-4, IL-6, TNF, and IFN-γ at 22 days after infection and increases in the levels of IL-2, IL-1, and IL-10 in infected mice at 35 days." (PMID 39899646, 2025). "Since TNF-α can stimulate ICAM-1 expression, we evaluated the infection rate of HBMEC and HUVEC in the presence of TNF-α." (PMID 40141288, 2025). "Supporting these findings, elevated serum cytokines such as TNF-α, IL-6, MCP-1, and MIP-1α confirmed that PMSS infection triggers a more robust inflammatory response than SS." (PMID 41183799, 2025). "In general, an increase in the RGE of the pro-inflammatory cytokines IFN-γ and TNF-α, as well as the anti-inflammatory cytokine IL-10, was observed in infected animals (IB1 and IB2) throughout the infection (Figs 2a1, 2c1, and 2e1)." (PMID 40743218, 2025). "In brief, RGG-expressing ECs were exposed to long-term inflammation (TNFα [10ng/mL]; 6 days) to induce senescence, followed by exogenous Sun1-FLAG infection." (PMID 40777343, 2025). "SGE-enhanced dissemination of virus to joint tissues resulted in higher upregulation of key arthritogenic cytokine transcripts, including TNF-alpha and IL-6, and the chemokines CXCL2, CCL2, and CXCL10 at day 7 post infection." (PMID 41362756, 2025). "Serological analysis revealed a progressive increase in TNF-α, IL-6, and IFN-γ levels with increasing infection severity, with statistically significant differences among the groups (P<0.05)." (PMID 40677522, 2025). "The expression of TNF-α, IL-1β, IL-6, IL-10, TGF-β, and hepcidin mRNA in WT increased sharply and reached a peak on day 1 post-infection with A. hydrophila, followed by a decrease." (PMID 40298788, 2025). "In parallel, proinflammatory cytokines (IL-1β, TNF-α, IL-6, IFN-α, and IFN-β) were measured, only IL-6 was significantly increased following SUCNR1 knockdown upon infection." (PMID 41492386, 2025). "The membrane form of TNF promotes the proliferation of both CD3+TCRαβ+ and CD3+TCRαβ− macrophages at infection sites." (PMID 40427602, 2025). "The data indicated that IL-1β, IL-6, IL-8, IL-18, TNF-α, and COX-2 mRNA levels in the spleen in the infection group were significantly upregulated (p < 0.001)." (PMID 40427533, 2025). "ELISA further showed dose-dependent reductions in the release of key inflammatory mediators: interferon-β (IFN-β), tumor necrosis factor-α (TNF-α), and interleukin-6 (IL-6), all of which were significantly different (all p < 0.05) from those in WT infection." (PMID 41301507, 2025). "Mast-cell-derived cytokines and chemokines facilitate the migration of dendritic cells (DCs; TNF-α and CCL20) and effector T cells (CXCL10/IP10 and CCL5/RANTES) to the infection site and draining lymph nodes." (PMID 40867663, 2025). "Cytokines, such as interleukins (e.g., IL-6) and tumor necrosis factor-alpha (TNF-α), play a dual role during infection." (PMID 40227362, 2025). "The levels of IL-6, TNF-α, and MCP-1 at 7 dpi in the doxycycline 25 mg/kg and omadacycline 10 and 15 mg/kg treatment groups were significantly lower than the infection control group." (PMID 41165324, 2025). "Ovarian hormones profoundly influence immune factors within the endometrium, including TNF-α and IL2, which are critical for infection prevention, endometrial preparation for implantation or menstruation, and subsequent repair." (PMID 40028534, 2025). "In immunocompetent mice, we observed increased mRNA levels of interferon gamma (IFNγ), tumor necrosis factor alpha (TNFα), PTGS2/COX-2, and interleukin (IL)-17A at the beginning of infection." (PMID 40586570, 2025). "The secretion of IL-1β, IL-6, and TNF-α was detected using ELISA, while the intracellular survival of Mtb was assessed by CFU counting 24 h post-infection." (PMID 39996735, 2025).
infection (continued). "The secretion of IFN and proinflammatory cytokines can rapidly recruit intrinsic immune cells to the site of infection and form a “positive feedback” loop under the stimulation of cytokines such as IFN-γ, TNF-α, and IL-6." (PMID 40283905, 2025). "Following infection with S. parauberis PH0710, TNFα expression was significantly downregulated in the gills and heart throughout most of the infection period." (PMID 40723580, 2025). "Various cell signaling cytokines such as tumor necrosis factor-alpha (TNF-alpha), interferon-gamma (IFN-gamma), interleukin-6 (IL-6), and interleukin-10 (IL-10) are activated during infection, facilitating immune cell differentiation." (PMID 40086236, 2025). "This pattern resembles the cytokine-mediated induction reported during Mab infection of THP-1 macrophages, which led to elevated expression of TNF-α, CCL4, IL-8, and IL-1β." (PMID 40762982, 2025). "In murine models, RSV mono-infection induced minimal TNF-α and IL-6 levels, whereas IAV mono-infection significantly elevated these cytokines." (PMID 40005506, 2025). "The TLR signaling pathways stimulate the synthesis of proinflammatory cytokines, including interleukin (IL), tumor necrosis factor (TNF), and type I interferon (IFN), which collectively attract various immune cells to the site of infection." (PMID 40576660, 2025). "There was an significantly increase in levels of interleukin 6 (IL-6) and tumor necrosis factor-α (TNF-α) levels after COVID-19 infection, and the cytokine levels decreased as the infection was contained." (PMID 40295300, 2025). "Both infected animals show two distinct peaks of TNF-α RGE in the early and late days of infection (Fig 2a1)." (PMID 40743218, 2025). "In agreement with that, after infection by L. (V.)braziliensis, the chimeras also generated stronger IDR responses and secretions of IFN-γ, TNF-α, and IL-10, suggesting a regulatory profile." (PMID 40666521, 2025). "While TNFα plays a central role in driving inflammation, IL8 is primarily involved in the activation and recruitment of neutrophils to the site of infection." (PMID 41256851, 2025). "The group also observed increased apoptosis, altered energy balance and secretion of various proinflammatory cytokines (IL-1β, TNF-α, IFN-γ, IL-6, IL-8 and MCP-1) in the presence of collagen, all of which favors host ability to control infection." (PMID 40406522, 2025). "Infection triggers a strong and rapid innate immune response, leading to the production of high levels of cytokines, including IFN and tumor necrosis factor-alpha (TNFα)." (PMID 40284971, 2025). "Compared with the PBS + infection and CpG + infection groups, both the rEg.P29T+B + CpG + infection and rEg.P29 + CpG + infection groups exhibited significantly higher levels of IFN-γ, IL-2 and TNF-α." (PMID 40266142, 2025). "Tumor necrosis factor-α (TNF-α), interleukin (IL)-1β, and IL-6 are cytokines produced by the immune system during the initial stages of infection." (PMID 40072101, 2025). "The heightened infection risk in GD may be attributable to dysfunction of immune cells, including monocytes, macrophages, dendritic cells, T cells, and B cells, as well involvement of cytokines, such as MCP1/CCL2, CXCL8/IL8, CXCL1, IL-1β, IFNγ, and TNFα, are implicated in GD progression." (PMID 40980139, 2025). "Infection of PNEs with RV-A16 at MOI 0.01 or MOI 1 for 24 h resulted in the upregulation (> twofold) of 6 cytokines (IL-1β, IL-1α, IFN-γ, I-309, TNF-α and IL-11)." (PMID 40916026, 2025). "Overall, children developed a SARS-CoV-2–specific CD4+ T cell response early in the course of infection with multiple effector functions, marked by potent production of IFN-γ, TNF, and IL-2, and preferential expression of CXCR3." (PMID 40906527, 2025). "During the later stages of infection, TRIM38 negatively regulates the TLR3/4 signaling, consequently suppressing the production of proinflammatory cytokines including TNF-α, IL-1β, and IL-6." (PMID 40006954, 2025).